IL6 (interleukin 6)
Diseases named in the same sentence as IL6 in open-access papers (continued):
Sharing a sentence is not in itself a finding about the gene and the disease.
Sepsis (continued). "IL-6 levels are increased in patients with infectious complications and are used clinically to provide a quantitative assessment of sepsis severity (42, –, 44)." (PMID 31818960, 2020). "We therefore reasoned that inflammatory mediators, such as TNF-α, IL-1β, and IL-6, contained within the septic mesenteric lymph play an indispensable role in the lung injury induced by sepsis." (PMID 33145344, 2020). "Regulatory T cell-derived exosomes increased IL-10 and decreased IL-6 production of dendritic cells upon LPS stimulation, indicating their contribution to immunosuppression in sepsis." (PMID 33013905, 2020). "Biomarkers of sepsis so far evaluated in horses include interleukin-1β (IL-1β), interleukin-10 (IL-10), interleukin-6 (IL-6), serum amyloid A (SAA), soluble CD14 (sCD14) and procalcitonin." (PMID 33148245, 2020). "In an ALI rat model caused by cecal ligation and puncture-induced sepsis, two independent laboratories demonstrated that the protein levels of TNF-α and IL-6 in BALF measured by ELISA were highest at 6 h and declined at later time points (12 and 24 h)." (PMID 32024527, 2020). "There is a strong association between the levels of systemic inflammatory mediators including IL-6 and the development of sepsis-induced AKI, suggesting a key responsibility of these mediators, including proinflammatory cytokines." (PMID 32089648, 2020). "Administration of 5-MTP to another sepsis model i.e. cecum ligation and perforation model also reduces serum IL-1β and IL-6 to the basal level." (PMID 32635910, 2020). "A wealth of research has corroborated that inflammatory cell infiltration and proinflammatory cytokines, including TNF‐α, IL‐6 and IL‐1β, play a vital role in the pathological process of sepsis." (PMID 32881263, 2020). "It was found that the abnormality of the coagulation function highly suggested the occurrence of sepsis and the other parameters represented by inflammatory factors including IL-2R, IL-6, and hs-CRP had a moderate predictive value on coagulopathy." (PMID 33747973, 2020). "The authors also concluded that the presence of both MIAC and HCA and a higher level of IL-6 were related to early-onset sepsis and neonatal morbidity." (PMID 33077789, 2020). "For example, circ-4099 is induced by inflammatory mediators, such as TNF-α and circRNA_0038644, and has been demonstrated to regulate the expression of NF-κB in sepsis, while IL-6 is regulated by circ_007893." (PMID 32630422, 2020). "Inclusion of supplementary sepsis markers (such as procalcitonin or interleukin 6) to be compared against presepsin would probably improve the value of our results." (PMID 33374939, 2020). "The authors concluded that IL-6 is a valuable biomarker for diagnosing sepsis in accordance with the latest Sepsis-3 definition." (PMID 33198109, 2020). "The data from clinical studies of sepsis showed that the plasma concentrations of IL-1β, IL-6, IL-8, MCP-1, IL-10, and IL-4 were significantly higher in non-survivors when compared with survivors." (PMID 32153410, 2020). "In the sepsis patients, the serum levels of the proinflammatory cytokines IL-6, IL-8, MCP-1, and IL-10 were strikingly higher than those in healthy controls, and the serum levels of IL-1β were slightly elevated." (PMID 32826331, 2020). "In a mouse sepsis model, Nrf2 disruption after DEPe exposure was related to changes in the regulation of IL-6 expression through NF-κB activation." (PMID 33008094, 2020). "Recently, a commercial IL-6 signaling-related drug was used as a potential therapeutic for the treatment of rheumatoid arthritis and sepsis." (PMID 32766286, 2020). "In the sepsis+MLD group, the mRNA expression of TNF-α, IL-1β, and IL-6 in the lung was significantly decreased, compared with the sepsis group (p < 0.05)." (PMID 33145344, 2020).
Sepsis (continued). "Based on the ROC curves, the diagnostic value of IL-6, sTREM-1, PCT, and CRP in an acute inflammation diagnosis (especially in SIRS and sepsis) and the prognostic value of febrile disease course were evaluated." (PMID 32655314, 2020). "In the liver, puerarin inhibited the transcription of inflammatory factor TNF-α, IL-6, and IL-1β and protected hepatocyte apoptosis in sepsis mouse models." (PMID 32457606, 2020). "As a systemic inflammatory response,inflammation-related serum C-reactive protein (CRP), procalcitonin (PTC), andinterleukin (IL-6) have been used in the diagnosis of sepsis, but theirspecificity and sensitivity are limited by different conditions." (PMID 32578720, 2020). "The aim of this study was to evaluate the diagnostic and prognostic value of IL-6 and sTREM-1 in the course of SIRS and sepsis in children with reference to routinely used CRP and PCT." (PMID 32655314, 2020). "The aim of this study was to evaluate the diagnostic and prognostic value of IL-6 and sTREM-1 in the course of acute inflammation among children, especially taking into consideration SIRS and sepsis with reference to routinely used CRP and PCT." (PMID 32655314, 2020). "Of these cytokines, tumor necrosis factor-α (TNF-α), interleukin-6 (IL-6) and interleukin-1β (IL-1β), which were produced excessively in the early stage of sepsis, have been found to have potential depressive effects on cardiac function." (PMID 32448150, 2020). "Lastly, patients with severe COVID-19 pneumonia can trigger a state of sepsis that can induce the release of inflammatory cytokines such as IL-6, IL-8, TNF-α, among others that can promote the activation of a hypercoagulability disorder." (PMID 32841275, 2020). "This is similar to the CLP model presented in this study, where while serum IL-6 concentration remains constant between 1 and 2 days of sepsis initiation, CD14 increased." (PMID 33135636, 2020). "Studies indicate that proinflammatory cytokines/chemokines, such as TNFα, IL-6, IL-1β, or MCP-1, etc., released of from activated microglia are important mediators for sepsis-associated brain inflammation." (PMID 32070376, 2020). "Under septic conditions, pro‐inflammatory cytokines, such as TNFα and IL‐6, evoke cytokine storms, which are responsible for tissue damage during sepsis." (PMID 32394600, 2020). "In our results, pulmonary H&E showed typical inflammatory infiltration in sepsis-associated ALI, and decreased plasma IL-6/TNF-α through MSCs treatment, effectively alleviated inflammatory infiltration, and reduced bleeding and edema." (PMID 32894198, 2020). "LPS is a cytotoxic agent that can induce inflammatory response and increase the expressions of inflammatory factors TNFα, IL-6, IL-8 and IL-1β, leading to sepsis." (PMID 32484206, 2020). "In a cohort of 44 patients with severe sepsis and 15 healthy controls, IL-10 and IL-6 levels were substantially elevated in both serum and SBF in the septic patients." (PMID 33224151, 2020). "Studies have found that the release of inflammatory cytokines, such as tumor necrosis factor (TNF-α) and interleukins (IL-1β and IL-6) increases, and promotes many immunopathological processes in sepsis, which are often referred to as “cytokines storm”." (PMID 33584285, 2020). "A previous study conducted among 34 neonates with culture confirmed and clinical sepsis reported a cut-off value for IL-6 at 20 pg/mL, with 91% sensitivity, 74% specificity, 78% PPV, and 89% NPV." (PMID 33233806, 2020). "XBJ can stimulate an increase in the number of Treg cells in mice with sepsis and can reduce the levels of TNF-α and IL-6 in the serum to increase the survival rate of mice with sepsis." (PMID 32082396, 2020). "PCT and IL-6 are also often examined in cases wherein a more severe infection, such as sepsis, is suspected because these markers are reportedly better in detecting sepsis than CRP." (PMID 33211747, 2020).
Sepsis (continued). "miR-223, as a pro-inflammatory factor, is involved in several signaling pathways that control inflammatory responses and infection reaction activation, such as negative regulation of STAT3 and IL-6 expression during sepsis." (PMID 33292630, 2020). "When ONB/MPA treatment was employed in murine models of LPS- and CLP-induced sepsis, we observed significant downregulation of growth factors and cytokines (i.e., IL-2, IL-6, and TNF-α)." (PMID 32226527, 2020). "An increased release of catecholamines occurs in the initial stage as well as in the acute and late stage of sepsis and is enhanced by the released pro-inflammatory cytokines (Interleukin (IL)-6, Tumor Necrosis Factor (TNF)-α)." (PMID 32708472, 2020). "We detected much significant higher levels of PCT, CRP, and IL-6 in the proved sepsis group than the suspected neonatal sepsis cases (p ≤ 0.001, 0.001, and 0.004, respectively)." (PMID 33061986, 2020). "Elevated levels of IL-6 and PCT are important risk factors for the development of SIRS/sepsis in children with fever." (PMID 32655314, 2020). "The level of IL-6 can be used in evaluating the prognosis of sepsis, as the higher the value, the more severe the sepsis." (PMID 33419284, 2020). "IL-10 is a crucial anti-inflammatory cytokine and immune support factor and also mediates the downregulation of proinflammatory cytokines such as TNF-α and IL-6 at the early stage of sepsis." (PMID 33376482, 2020). "The APOE mRNA and protein levels in septic patients were significantly lower than those of the healthy controls (p = 0.024 and p < 0.001, respectively), while the levels of TNF-α, IL-6, and IL-1β were elevated in sepsis patients." (PMID 32978453, 2020). "In the current study, miR-19b-3p level was determined to be negatively associated with serum levels of both IL-6 and TNF-α in sepsis patients." (PMID 32188465, 2020). "Studies have suggested that the measurement of IL-6 levels in the plasma from blood samples during the onset of sepsis can assist in the early identification of this condition and initiation of adequate treatment." (PMID 32273831, 2020). "Other cytokines, such as IL-1β, IL-6, and IL-10, can be used for the diagnosis of sepsis and evaluating the inflammatory responses and the prognosis for ARDS patients." (PMID 32566670, 2020). "Transcriptomic upregulation of CRP is induced by increased levels of interleukin-6, which is commonly elevated in the early phases of sepsis." (PMID 32932765, 2020). "Our results showed that females expressed higher IL-6 and TNFα than males in sepsis, and trained immunity exacerbated this trend." (PMID 32793229, 2020). "Another disadvantage is the fact that IL-6 levels rise not only in sepsis but also in hypoxia, fetal distress, preterm birth, usage of antenatal steroids and meconium aspiration syndrome." (PMID 33419284, 2020). "They found that SFI significantly lowered IL-6 levels in patients with severe sepsis and regulated the balance between pro- and anti-inflammatory factors, thus, improving the therapeutic effect." (PMID 32848729, 2020). "This is similar to the regulatory effect of L. rhamnosus L34, which inhibited the translocation of intestinal pathogens as well as decreased IL-6 level induced by these pathogens, thereby attenuating the sepsis of murine models." (PMID 33042071, 2020). "Compared to healthy control subjects, all subgroups have higher IL-6 and IL-8 levels at 1, 4, 7, and 14 days after sepsis onset (p < 0.01)." (PMID 32381107, 2020). "So, in this study, we were interested in evaluating the CRP, PCT, and IL-6 as sepsis markers for early diagnosis of sepsis in neonates." (PMID 33061986, 2020). "During sepsis in mice, MDSCs accumulate in the late or chronic phase and both the pro-inflammatory cytokine IL-6 and the anti-inflammatory cytokine IL-10 play a critical role in the mediation of MDSC expansion." (PMID 32931721, 2020).
Sepsis (continued). "In contrast, ADAR1 overexpression significantly reduced IL-6 levels in the spleen, consistent with IL-6 function as the main inflammatory factor, which attenuates the inflammatory response in sepsis that is inhibited by ADAR1." (PMID 32273831, 2020). "IL-6 is a pivotal cytokine with diverse physiological functions and increasing IL-6 level is one of the hallmarks of sepsis." (PMID 32641132, 2020). "This was in contrast with the findings of Ahmed and co-workers who found that presepsin was superior to IL-6 (AUCs of 0.934 and 0.751, respectively), although their study was focused on the diagnosis of early-onset sepsis." (PMID 32164268, 2020). "The authors also looked at cases of early- and late-onset sepsis and suggested that there was a significant difference in the concentrations of IL-6 and CRP between these two groups." (PMID 32164268, 2020). "Previous studies showed a correlation between the PCT and the CRP levels in the proved sepsis group after 12–24 h of admission in contrast to IL-6, which had a very short half-life and became undetectable 24 hours after the onset of infection." (PMID 33061986, 2020). "In sepsis, endotoxin stimulates the synthesis and release of various pro-inflammatory cytokines and factors, including TNFα, IL-1β, IL-6, Fas ligand (FasL), granzymes, etc., mainly by mononuclear macrophages." (PMID 32457606, 2020). "The proinflammatory cytokine IL-6 is critical for the progression of acute inflammatory diseases such as sepsis and ARDS." (PMID 32826331, 2020). "Significantly increased serum interleukin-6, tumor-necrosis-factor-alpha and interleukin-1-beta confirmed sepsis." (PMID 32661347, 2020). "Nanjo Y. has suggested that the use of colistin sulfate (subcutaneously injected at 1.0 mg per mouse) can reduce the levels of TNF-α, IL-6 and IL-1β in LPS-induced sepsis mouse model and lead to decreased toxicity." (PMID 33551807, 2020). "IL-6, TNF-α, IL-1β, and IL-12 are hallmark inflammatory mediators of sepsis that constitute the cytokine storm." (PMID 32153410, 2020). "The expression levels of TNF-α, IL-1β, and IL-6 mRNA in the intestine, liver, and lung of the rats in the sepsis group increased significantly, compared with the control and sham surgery groups." (PMID 33145344, 2020). "Increased blood levels of IL-6 and IL-10 have been clinically related to the high rate of mortality in patients with severe sepsis." (PMID 32117251, 2020). "The administration of anti-IL-6 antibody within 4 h after CLP was found to improve survival in a murine sepsis model." (PMID 32197507, 2020). "The hyper-inflammatory phase presents with dramatic increases of various potent cytokines (called a cytokine storm) including TNF-α and IL-6 in patients with sepsis, and in in vivo mice and human studies." (PMID 33382782, 2020). "The meta-analyses of TNF-α and IL-6 protein levels after two-challenges show similarities to the clinical sepsis samples." (PMID 33382782, 2020). "IL-6 is associated with the occurrence of MODS and sepsis together with IL-10 within 24 h after trauma." (PMID 32492963, 2020). "The concentration of IL-6 in the blood can provide insight into the severity of sepsis, septicemia, and infection in patients who require intubation and mechanical ventilation." (PMID 33167445, 2020). "Other studies have also reported a high production of cytokines in the context of sepsis, such as IL-6, as well as the chemokine MCP-1." (PMID 32197297, 2020). "Of the analyzed biomarkers, procalcitonin and IL-6 had potential usefulness in the diagnosis of SRIS/sepsis in feverish children." (PMID 32655314, 2020). "In sepsis, the vascular endothelium is activated by lipopolysaccharides (LPS) and/or inflammatory mediators including interleukin-6 (IL-6), tumor necrosis factor-α (TNF-α), and interleukin-1 (IL-1)." (PMID 32964021, 2020). "In the literature, most studies assessing the diagnostic value of IL-6 and sTREM-1 in SIRS/sepsis are related to adults." (PMID 32655314, 2020).
Sepsis (continued). "First, we investigated the prognostic value of individual biomarkers (PTX3, PCT, IL6, and lactate) or their combination in patients diagnosed with sepsis or septic shock according to the latest Sepsis-3 definitions." (PMID 32481464, 2020). "The potential prognoses of acute respiratory distress syndrome and sepsis using IL-6 expression levels have also been established." (PMID 33156843, 2020). "The induction of miR-199a in AMs during sepsis increases the release of pro-inflammatory cytokines (IL-1β, IL-6, and TNF-α), the MPO activity, ALI, and the high levels of CASP3, Bax and lowers the Bcl-2 levels." (PMID 32849610, 2020). "We aimed to conduct a prospective observational analysis to confirm the prognostic value of PTX3, PCT, IL6, and lactate in patients with sepsis or septic shock." (PMID 32481464, 2020). "Doxycycline ameliorated pulmonary inflammation in a murine polymicrobial sepsis model by decreasing levels of IL-1β, IL-6 and TNFα in plasma and lungs." (PMID 33142770, 2020). "Sepsis-related mediators, such as endotoxin and the pro-inflammatory cytokines IL-1β, IL-2, IL-6, TNF-α, and IFN-β, have been shown to induce high expression of iNOS." (PMID 33123008, 2020). "Patients with sepsis typically have elevated blood levels of endotoxins and cytokines [e.g., interleukin 6 (IL-6), IL-8, IL-10, and tumor necrosis factor alpha(TNF-α)]." (PMID 32144519, 2020). "Further investigations are needed to study the interaction of IL-6 and cardiac mitochondrial function with aging post-burn and/or complicated by sepsis." (PMID 32932869, 2020). "Studies by Taniguchi and coworkers 28 and Qiao and coworkers 29 demonstrated that dexmedetomidine reduces the concentrations of TNF-α and IL-6, and ameliorates mortality in rats with endotoxin or cecal ligation and intestinal puncture-induced sepsis." (PMID 33029092, 2020). "The lysosomotropic compound NB 06 down-regulates the expression of pro-inflammatory cytokines (e.g., IL-1B, IL-6 and IL-23A in LPS-stimulated macrophages and desipramine protects against sepsis-induced cardiac dysfunction in a murine sepsis model." (PMID 32668803, 2020). "A recent study by Deǧirmencioǧlu and co-workers calculated an AUC of 0.939 for the diagnosis of late-onset sepsis in preterm neonates, which was slightly outperformed by IL-6 (AUC of 0.959)." (PMID 32164268, 2020). "In a previous report, cats with sepsis were more likely to have detectable plasma IL-6 concentrations compared to cats with SIRS and controls, and greater IL-6 concentrations were associated with non-survival." (PMID 32548135, 2020). "In summary, Paeoniflorin and HSYA are key active compounds in XBJ for managing sepsis, protecting cardiac function, and controlling inflammation in the cardiac tissue partially by limiting the production of IL-6, IL-1β, and CXCL2." (PMID 33986658, 2020). "To delineate the potential mechanism underlying the alcohol LPS protection, we measured the serum level of IL-6, a representative cytokine to indicate the severity of sepsis." (PMID 32117233, 2020). "Anti-IL-17A antibodies downregulate CCL3, CXCL1, and IL-6 in cardiomyocytes of mice with sepsis induced by CLP, suggesting that IL-17A contributes to sepsis-induced cardiomyopathy." (PMID 32849528, 2020). "Both TNF-α and IL-6 are the central mediators of sepsis, which is uncontrolled inflammatory response which can result in multi-organ failure and even demise." (PMID 33028307, 2020). "IL-6 protein level is significantly elevated during acute phase of sepsis (in 4d since sepsis diagnosis) in critically ill patients compared to non-critically ill and healthy ones." (PMID 33382782, 2020). "In the early phase of sepsis, IL-6 is rapidly expressed and its concentration remains increased for a prolonged period compared to other inflammatory mediators." (PMID 32548135, 2020).